MRE11 (MRE11 double strand break repair nuclease)
Diseases named in the same sentence as MRE11 in open-access papers (continued):
Sharing a sentence is not in itself a finding about the gene and the disease.
breast carcinoma (continued). "For example, high expression of MRE11, a core protein of the MRN (MRE11/RAD50/NBS1) repair complex, enhances breast cancer cell proliferation and invasion and promotes DNA repair through STAT3." (PMID 32872659, 2020). "The MRE11 signaling pathway is not conserved across different cell types, with our prior report indicating that MRE11 mediates its effects in breast cancer via STAT3 and its downstream effectors cyclin D, Myc, and BCL-xL." (PMID 33927349, 2021). "MRE11, RAD50, and NBS1 genes were identified as genes with moderate penetrance for breast cancer." (PMID 31767017, 2019). "The interaction between the meiotic recombination 11 homolog A (MRE11) oncoprotein and breast cancer recurrence status remains unclear." (PMID 28133604, 2017). "However, the occurrence of germline Mre11 alterations in a minority of breast cancer patients observed in these studies has not been confirmed in ample case population studies." (PMID 37754262, 2023). "Within Asia, a South Korean study of 235 patients at high-risk for hereditary breast cancer and were confirmed not to have a BRCA1/2 mutation were tested with massively parallel sequencing, and 3.6% were found to have pathogenic germline mutations in CHEK2, PALB2, MRE11 and RAD50." (PMID 30093976, 2018). "Another limitation is that sequence data was unavailable for MRE11, RAD50 or NBS1 in these specific patients and it was not possible to investigate in patients with familial breast cancers." (PMID 34782604, 2021).
ataxia-telangiectasia-like disorder (31 papers, 2006 to 2023). An autosomal recessive condition caused by mutation(s) in the MRE11A gene, encoding double-strand break repair protein MRE11. "MRE11 mutants have been linked to ataxia-telangiectasia-like disorder (ATLD) and are highly correlated with multiple types of cancers." (PMID 36050397, 2022). "Mutations in MRE11 are responsible for the human radiation sensitivity disorder Ataxia-telangiectasia-like disorder (ATLD), which is characterised by defective checkpoint responses and high levels of chromosomal abnormalities." (PMID 33558481, 2021). "In contrast to ATM, Mre11 is essential for cell survival and homozygous hypomorphic Mre11 mutations lead to a genetic disease which is phenotypically similar to A-T called ataxia telangiectasia-like disorder." (PMID 32309213, 2020). "Cells with a mutation in the MRE11 gene, derived from a patient with ataxia-telangiectasia-like disorder, and cells in which MRE11 was knocked down had defects in dsDNA-induced type I IFN production." (PMID 32283785, 2020). "Ataxia telangiectasia-like disorder is caused by mutations in MRE11, part of the MRN complex which associates with NBS1, and is extremely rare, with few patients reported worldwide [92, 93•]." (PMID 32648006, 2020). "For instances, mutations in MRE11 gene lead to ataxia-telangiectasia-like disorder (ATLD), which is quite rare with only a few cases reported." (PMID 31767017, 2019). "Mutations of the MRN complex subunit MRE11 cause the hereditary cancer-susceptibility disease ataxia-telangiectasia-like disorder (ATLD)." (PMID 28436950, 2017). "MRE11 germline mutations that cause a lethal phenotype in mice are rarely encountered in humans and lead to an Ataxia telangiectasia-like disorder (ATLD)." (PMID 24927325, 2014). "Rarely, hypomorphic mutations in MRE11 occur in individuals with "Ataxia-Telangiectasia-Like-Disorder" (ATLD)." (PMID 17683622, 2007). "Germline BRCA2 mutations predispose to ovarian, breast and pancreatic cancer, while a germline MRE11 mutation is associated with an ataxia telangiectasia-like disorder." (PMID 16417627, 2006). "In addition to TDP2 deficiency associated with SCAR23, MRE11 deficiency also results in exclusively neurological phenotypes, including cerebellar degeneration and progressive ataxia, and described as ataxia telangiectasia-like disorder (ATLD)." (PMID 34899270, 2021). "Cells from patients with Ataxia-telangiectasia-like disorder (ATLD) express a hypomorphic truncated Mre11 mutation." (PMID 22937147, 2012). "Mutations in MRE11, RAD50, and NBS1 cause human genomic instability syndromes Ataxia-Telangiectasia-like disorder (A-TLD), NBS-like disorder (NBSLD), and Nijmegen Breakage Syndrome (NBS), respectively." (PMID 35153719, 2021). "Varying degrees of antibody deficiency have also been noted in chromosomal instability syndromes such as ataxia-telangiectasia (A-T, ATM mutations), Nijmegen breakage syndrome (NBS, NBS1 mutations), and ataxia-telangiectasia-like disorder (ATLD, MRE11 mutations)." (PMID 20805886, 2010). "In humans, mutations in the genes encoding Mre11 and NBS1 result in two rare chromosomal instability syndromes: ataxia-telangiectasia-like disorder (ATLD) and Nijmegen breakage syndrome (NBS)." (PMID 18575580, 2008). "Nevertheless, mutations affecting, but not abolishing, the binding of MRE11 to the other two subunits of the MRN complex lead to ataxia telangiectasia-like disorder (ATLD) showing phenotypes distinct from NBS." (PMID 23443494, 2013). "Loss of Nbs1 or Mre11 is embryonic lethal and mutations in NBS1 and MRE11 lead to the chromosomal instability disorders Njimegen breakage syndrome (mutation in NBS) and ataxia telangiectasia-like disorder (ATLD; mutation in Mre11)." (PMID 21037856, 2010).
ataxia-telangiectasia-like disorder (continued). "For instance, Mre11, Nbs1, ATM and BRCA1, which play critical roles in DNA damage checkpoint and DSB repair are linked ataxia-telangiectasia-like disorder (ATLD), Nijmegen breakage syndrome (NBS), ataxia-telangiectasia and familial breast cancer, respectively." (PMID 23468639, 2013). "In addition, mutations in DNA damage signalling kinase ATM have been linked to Ataxia-telangiectasia, whereas Ataxia-telangiectasia-like disorder (ATLD) and Nijmegen breakage syndrome (NBS) are caused by mutations in two components of the MRN complex, MRE11 and NBS1 respectively." (PMID 23741394, 2013). "We infected cells from patients with ataxia telangiectasia (A–T) and ataxia telangiectasia-like disorder (A-TLD) that lack functional ATM and Mre11 respectively, and compared them to matched controls in which ATM or Mre11 had been reconstituted." (PMID 21698222, 2011).
Nijmegen breakage syndrome (30 papers, 2004 to 2023). Nijmegen breakage syndrome is a rare genetic disease presenting at birth with microcephaly, dysmorphic facial features, becoming more noticeable with age, growth delay, and later-onset complications such as malignancies and infections. "The common mutation in NBS1 (657del5) causing Nijmegen breakage syndrome impairs NBS1 interaction with MRE11 and RAD50." (PMID 29973640, 2018). "Clearly the MRN complex plays a very important role in ATM function, particularly considering the similarity in clinical phenotypes of patients lacking ATM (A-T) compared with patients expressing hypomorphic alleles of MRE11 or RAD50 (A-T-like Disorder) or Nbs1 (Nijmegen Breakage Syndrome)." (PMID 23525106, 2013). "In this study, we found that phosphorylation of CtIP by cell-cycle-dependent kinases CDKs modulates CtIP interaction with Nbs1, a component of the Mre11-Rad50-Nbs1 complex that is associated with Nijmegen breakage syndrome (NBS)." (PMID 23468639, 2013). "Examples include NBS1 and MRE11, which are both involved in DSB repair and are associated with Nijmegen breakage syndrome and ataxia–telangiectasia-like disorder, respectively." (PMID 37296624, 2023). "In addition, mutations in the Nbs1 gene, can cause Nijmegen breakage syndrome (NBS), whereas Mre11 mutations resulted in Ataxia telangiectasia-like disease syndrome (ATLD)." (PMID 32509463, 2020). "Studies showed that hypomorphic mutations in MRE11 and NBS1 lead to Ataxia telangiectasia disorder and Nijmegen breakage syndrome, a rare autosomal recessive disorder." (PMID 31395037, 2019). "Mutations in ATM, Mre11 and NBS1 are found in patients with Ataxia Telangiectasia (A-T), Ataxia Telangiectasia-like disorder (A-TLD) and Nijmegen breakage syndrome (NBS), respectively." (PMID 29254281, 2017). "These include the clinically similar Ataxia telangiectasia (AT), AT like disease (ATLD), Nijmegen Breakage Syndrome (NBS) and NBS like disorder (NBSLD), caused by mutations in the ATM, MRE11, NBS1 and RAD50 genes respectively." (PMID 26160886, 2015). "Hypomorphic mutations in Mre11 and Nbs1 give rise, respectively, to an A-T-like disease (ATLD) and Nijmegen breakage syndrome (NBS)." (PMID 15138496, 2004). "In humans, homozygous hypomorphic mutations in MRE11, NBN (coding for the NBS1 protein) and RAD50 genes cause ataxia telangiectasia‐like disorder (ATLD‐OMIM:604391), Nijmegen breakage syndrome (NBS‐OMIM:251260) and NBS‐like disorder (NBSLD‐OMIM:613078), respectively." (PMID 35839783, 2022). "As such, cells derived from ataxia-telangiectasia-like disease (ATLD) and Nijmegen breakage syndrome (NBS) patients that express mutant forms of either MRE11 or NBS1, respectively, display greatly reduced ATM activation and a predisposition to cancer development." (PMID 27568553, 2016). "Hypomorphic, biallelic mutations in the MRE11, RAD50 and NBN genes are linked to recessive genetic conditions, ataxia telangiectasia like disorder (AT-LD), NBS-like and Nijmegen breakage Syndrome (NBS), respectively, some of which are characterized by increased risk of cancer." (PMID 24093751, 2013).
ovarian carcinoma (30 papers, 2013 to 2025). A malignant neoplasm originating from the surface ovarian epithelium. "Lower expression of MRE11 was associated with better overall survival in a cohort of patients with ovarian cancer treated with platinum drugs (TCGA dataset, P < .05)." (PMID 38551731, 2025). "Here, we show that effecting an MRE11 blockade using a prototypical inhibitor (Mirin) induces synthetic lethality (SL) in BRCA2-deficient ovarian cancer cells, HeLa cells, and 3D spheroids compared to BRCA2-proficient controls." (PMID 37446144, 2023). "Taken together, the data provide evidence that MRE11 blockade or depletion is associated with selective toxicity in BRCA2-deficient ovarian cancer cells." (PMID 37446144, 2023). "We have recently shown that MRE11 upregulation is a frequent event in ovarian cancers and is associated with poor progression-free survival (PFS) and platinum resistance in patients." (PMID 37446144, 2023). "We then proceeded to evaluate potential mechanisms of resistance to MRE11 blockade in BRCA2-deficient ovarian cancer cells." (PMID 37446144, 2023). "Pre-clinically, Mre11 depletion or blockade not only reversed platinum resistance, but we also identified a synthetic lethality approach targeting Mre11 in XRCC1 deficient platinum sensitive ovarian cancers." (PMID 35853939, 2022). "The first report of MRE11-associated ovarian carcinoma was from a cohort of 151 women with hereditary breast or ovarian cancer, of whom one was found to have a germline MRE11 mutation." (PMID 35159349, 2022). "Heikkinen and colleagues screened 151 families with signs of hereditary breast and/or ovarian cancer for germline mutations in the Mre11 complex genes." (PMID 26075229, 2015). "Moreover, MRE11 inhibition was synthetically lethal in platinum-sensitive XRCC1-deficient ovarian cancer cells and 3D-spheroids." (PMID 37509263, 2023). "To validate this hypothesis, in the current study, we evaluated MRE11 blockade as a synthetic lethality strategy in BRCA2-deficient ovarian cancers." (PMID 37446144, 2023). "Importantly, Mre11 inhibition was synthetically lethal in platinum sensitive XRCC1 deficient ovarian cancer cells and 3D-spheroids." (PMID 35853939, 2022). "Our data also indicates that Mre11 deficient epithelial ovarian cancers may also be suitable for PARP targeted synthetic lethality approach." (PMID 35853939, 2022). "We have also investigated Mre11 and Rad50 variants in ovarian cancer cells." (PMID 33435622, 2021). "Molecular variants of the MRE11 gene have been identified in breast and ovarian cancer." (PMID 24079363, 2013). "However, in the current study, we did not observe selective toxicity for FEN1 inhibitor in ATM-deficient HeLa cells or MRE11 deficient ovarian cancer cells implying that this phenomenon could be cell line dependent." (PMID 33919707, 2021). "Analysis of a clinical cohort of ovarian cancers treated with platinum chemotherapy revealed that tumours with high PRDX1/high ATM or high PRDX1/high MRE11 expression manifested aggressive phenotypes and poor patient survival." (PMID 40387816, 2025). "Ovarian cancers with high PRDX1/high ATM or high PRDX1/high MRE11 expression showed poor survival and an aggressive phenotype." (PMID 40387816, 2025). "The expression of PRDX1, ATM, and MRE11 were investigated using Tissue MicroArrays (TMA) of 331 consecutive ovarian epithelial cancer cases treated at Nottingham University Hospitals (NUH) between 1997 and 2010." (PMID 40387816, 2025). "Here, we conducted immunohistochemical studies of BRCA2 and MRE11 co-expression in 226 evaluable sporadic epithelial ovarian cancers." (PMID 37446144, 2023). "We have recently shown that MRE11 overexpression is a predictive biomarker of platinum resistance in human ovarian cancer tumours." (PMID 37446144, 2023). "The studies of MRN complex (RAD50, MRE11, NBN) mutations and ovarian cancer summarized above are contradictory and are insufficient to determine ovarian cancer risk." (PMID 35159349, 2022).
ovarian carcinoma (continued). "We have recently shown that the Mre11 partners, Rad5022 and Nbs121 are also predictors of platinum resistance in ovarian cancers." (PMID 35853939, 2022). "We conclude that pharmaceutical development of Mre11 inhibitors is a viable clinical strategy for platinum sensitization and synthetic lethality in ovarian cancer." (PMID 35853939, 2022). "Here, we have demonstrated a strong positive correlation between Mre11, Rad50 and Nbs1 in clinical ovarian cancer cohorts." (PMID 35853939, 2022). "Pharmaceutical development of Mre11 inhibitors is a viable clinical strategy for precision oncology approaches in ovarian cancers." (PMID 35853939, 2022). "Pre-clinically, Mre11 depletion or blockade not only reversed platinum resistance, but targeting Mre11 in XRCC1 deficient platinum sensitive ovarian cancers also induced synthetic lethality." (PMID 35853939, 2022). "In the ovarian cancer genome atlas (TCGA) cohort (n = 498), Mre11 gene amplification was observed in a subset of serous tumours (5%) which correlated highly with Mre11 mRNA levels (p < 0.0001)." (PMID 35853939, 2022). "In co-immunoprecipitation experiments, in ovarian cancer cell lines, we also observed that Mre11 physically interacted with Nbs1, Rad50, XRCC1 and LIG3 consistently in PEO1 cells." (PMID 35853939, 2022). "Pre-clinically, Mre11 depletion by gene knock down or blockade by small molecule inhibitor (Mirin) reversed platinum resistance in ovarian cancer cells and in 3D spheroid models." (PMID 35853939, 2022). "Taken together, the data suggest that increase in Mre11 levels after cisplatin treatment is a feature of ovarian cancer cell lines." (PMID 35853939, 2022). "Taken together, the data provides evidence that Mre11 is an attractive drug target in epithelial ovarian cancer." (PMID 35853939, 2022). "Mre11 blockade is a platinum sensitizer and can induce synthetic lethality in XRCC1 deficient-platinum sensitive ovarian cancers." (PMID 35853939, 2022). "Investigation of the expression of Mre11 was carried out on tissue microarrays (TMA) of 331 consecutive ovarian epithelial cancer cases treated at Nottingham University Hospitals (NUH) between 1997 and 2010." (PMID 35853939, 2022). "The data in its entirety therefore provides compelling clinical and pre-clinical evidence that targeting Mre11 is an attractive anti-cancer strategy in ovarian cancers." (PMID 35853939, 2022). "MRE11 knockdown led to moderately increased sensitivity towards the PARP inhibitor BMN673 in one ovarian carcinoma cell line in vitro." (PMID 28073364, 2017). "In order to further clarify the functional phenotype of Olaparib resistance caused by MRE11:p.K464R mutation, we selected two ovarian cancer cell lines (SKOV3 and A2780) and generated stable cell lines expressing MRE11WT and MRE11K464R protein after MRE11 knockout, respectively." (PMID 37759323, 2023). "Our data suggest that MRE11 is an attractive anti-cancer target in ovarian cancers." (PMID 37446144, 2023). "Interestingly, however, Mre11 depletion reversed resistance in platinum resistant ovarian cancer cell lines." (PMID 35853939, 2022). "Here we have comprehensively evaluated Mre11 in ovarian cancer." (PMID 35853939, 2022). "Here we have comprehensively evaluated Mre11 in epithelial ovarian cancers." (PMID 35853939, 2022). "The data further supports the hypothesis that Mre11 either directly or indirectly through its interaction with other DNA repair factors could influence platinum resistance in ovarian cancers." (PMID 35853939, 2022). "Next, we explored if Mre11 blockade could also be exploited for synthetic lethality in platinum sensitive ovarian cancers." (PMID 35853939, 2022). "Taken together, the data provides clinical evidence high Mre11 may predict adverse clinical outcome and resistance to platinum therapy in ovarian cancer patients." (PMID 35853939, 2022).
ovarian carcinoma (continued). "Our data suggest that the mechanism of Mre11 overexpression in ovarian cancer is multifactorial; gene amplification, transcriptional upregulation, protein overexpression and altered sub-cellular localization may all contribute to Mre11 upregulation and platinum resistance in tumours." (PMID 35853939, 2022). "The relevance of other homologous recombination repair proteins, e.g. MRE11, RAD50, NBS1 (MRN complex) in ovarian carcinomas is unclear." (PMID 28073364, 2017). "The MRN complex (MRE11, RAD50, and NBN) is implicated in nonhomologous end joining DNA repair and has rarely been reported in association with ovarian cancer." (PMID 35159349, 2022). "Ovarian carcinomas with KRAS mutation showed frequent lack of NBS1 detection (p = 0.013, Fisher’s exact test) and a trend for MRE11 negativity (p = 0.08, Fisher’s exact test)." (PMID 28073364, 2017). "In a clinical cohort of ovarian cancer, we show that the patients whose tumours have high levels of expression of MRE11 and low levels of expression of BRCA2 have poor rates of PFS, implying that targeting MRE11 could be clinically relevant." (PMID 37446144, 2023). "Other mutations were uniquely enriched in HRD+ predicted cases of breast and ovarian cancers (BARD1, BRIP1, MRE11, RAD51D) and cancer cohorts outside breast and ovarian cancer (RAD51B), suggesting additional unique drivers of HRD that may be cancer-cohort specific." (PMID 35643464, 2022). "Whilst small molecule inhibitors of ATM and ATR are under clinical trial evaluation, Mre11 blockade could impair both ATM and ATR mediated pathways simultaneously and could be an effective strategy in ovarian cancers which frequently manifest genomic instability and replication stress." (PMID 35853939, 2022). "In epithelial ovarian cancer, where a lack of MRN complex protein detection was seen in 41% of the tumors, MRE11 knockdown increased sensitivity towards the PARP inhibitor BMN673." (PMID 37509263, 2023). "Frequent lack of MRE11, RAD50, NBS1 protein detection in type I human ovarian carcinomas is observed in EOC and our data suggests further investigation regarding sensitivity to PARP-inhibition in tumours lacking MRE11 expression." (PMID 28073364, 2017). "The objective of this study was to investigate the prevalence of lack of MRE11, RAD50, NBS1 protein detection in epithelial ovarian cancer (EOC)." (PMID 28073364, 2017). "Additionally, utilising the TCGA Ovarian cancer cohort in UCSC Xena, we observed a non-significant trend (p = 0.08) toward worse survival in patients with tumours that had high Mre11 copy numbers." (PMID 35853939, 2022).